PBDC1 (polysaccharide biosynthesis domain containing 1)
Synonyms: CXorf26; MGC874
Tractability: PROTAC: ubiquitination databases record sites on it; its protein half-life has been measured.
Gene: Protein-coding gene on chromosome X (76,173,034 to 76,178,755, forward strand). Ensembl gene ENSG00000102390.
Subcellular location (Human Protein Atlas): Nucleoplasm; Cytosol; Nucleoli
Gene Ontology:
Molecular function: protein binding; protein folding chaperone
Biological process: 'de novo' cotranslational protein folding
Homologues: Orthologues: macaque PBDC1 (97% identical), chimpanzee PBDC1 (85% identical), dog PBDC1 (79% identical), pig PBDC1 (79% identical), mouse Pbdc1 (72% identical), guinea pig PBDC1 (71% identical), rat Pbdc1 (60% identical), tropical clawed frog pbdc1 (45% identical), zebrafish pbdc1 (45% identical), Drosophila melanogaster CG7519 (32% identical), Caenorhabditis elegans Y54E5A.5 (27% identical).
Diseases named in the same sentence as PBDC1 in open-access papers:
PBDC1 is named in the same sentence as 1 disease in open-access papers, as found by Europe PMC text mining. Sharing a sentence is not in itself a finding about the gene and the disease.
PBDC1 shares sentences with these, for which no sentence is quoted: X-linked disease (1 paper).